KDM5B (lysine demethylase 5B)
Diseases named in the same sentence as KDM5B in open-access papers (continued):
Sharing a sentence is not in itself a finding about the gene and the disease.
prostate carcinoma (29 papers, 2010 to 2025). A carcinoma that arises from epithelial cells of the prostate gland. "The RNA and protein level of KDM5B was elevated in localized and advanced prostate carcinomas, and it was shown that KDM5B together with LSD1 was implicated in the regulation of expression of AR target genes." (PMID 40940894, 2025). "The loss of KDM5B inhibits the proliferation of prostate cancer cells by inhibiting the PI3K/AKT signaling." (PMID 39039611, 2024). "Increased expression of KDM1A and KDM5B is implicated in many cancer types, including prostate cancer (PCa)." (PMID 37152294, 2023). "In line with this, a novel CPI-455-based PROTAC degrader of KDM5B activated type I IFN signaling in prostate cancer cells." (PMID 40940894, 2025). "The use of microRNAs in regulating KDM5B was evaluated, and it was found that the expression of miR-29a inhibited the proliferation of prostate cancer cells and induced their apoptosis by decreasing the expression of KDM5B." (PMID 38004468, 2023). "KDM5B binds to androgen receptors (essential for prostate cancer development/progression) and enhances their transcriptional activity." (PMID 38004468, 2023). "Another recent study has shown that AKT inhibition decreases the expression of the KDM5 family, especially KDM5B (JARID1B) in PTEN-null prostate cancer." (PMID 37228649, 2023). "The knockout of Kdm5b was found to suppress prostate tumorigenesis in a Pten-null prostate cancer mouse model by reducing the levels of P110α/P85." (PMID 35805040, 2022). "KDM5B expression is higher in prostate cancer than in normal or benign tissues, and higher KDM5B expression is related to advanced tumors and poor prognosis." (PMID 35805040, 2022). "The forced miR-29a expression inhibited proliferation, and induced apoptosis in prostate cancer cells, by repressing KDM5B expression, whereas, by KDM5B targeting, miR-137 aided as a tumor suppressor in prostate carcinogenesis." (PMID 32751840, 2020). "KDM5B was found to be overexpressed in prostate cancer tissues, compared to benign tissues, and has been suggested as a potential therapeutic target." (PMID 32751840, 2020). "Recently, several KDM5B inhibitors have been identified and reported in different cancers such as the breast and prostate cancers." (PMID 33245716, 2020). "Earlier studies demonstrate that KDM5B is not only overexpressed in hormone-driven cancers such as the breast and prostate cancers, but also interacts with hormone receptors, ER and AR, to positively regulate their transcriptional activities." (PMID 33245716, 2020). "KDM5B, or JARID1B/PLU-1, has been previously identified as an oncogene in breast, lung, and prostate cancer, and is may be associated with stem cell-like properties." (PMID 37880235, 2023). "Furthermore, 5–6% of individuals with prostate cancer exhibit amplification of the KDM5B copy number, and less than 1% of them show the heterozygous deletion of KDM5B." (PMID 38004468, 2023). "Interestingly, AKT has been shown to positively regulate the expression of KDM5B by repressing miR-137 in PTEN-null prostate cancer, suggesting that KDM5B forms a feed-forward regulatory loop with PI3K/AKT signaling in prostate cancer." (PMID 35805040, 2022). "KDM5B also plays a key role in activating PI3K/AKT signaling in prostate cancer." (PMID 35805040, 2022). "Moreover, KDM5B knockdown significantly suppressed proliferation and decreased the proportion of cells in S and G2/M phase of prostate cancer cells." (PMID 35333349, 2022). "SKP2 inactivates KDM5B through ubiquitination in prostate cancer cells." (PMID 31776402, 2019). "Paradoxically, HEXIM1 upregulated KDM5B expression in prostate cancer." (PMID 31805991, 2019). "KDM5 family members are H3K4 demethylases; JARID1B (KDM5B) is upregulated in prostate cancer tissues and acts as an AR coactivator, while JARID1C (KDM5C), overexpressed in prostate cancer, emerged as a predictive marker for therapy failure in patients after prostatectomy." (PMID 29888169, 2018).
prostate carcinoma (continued). "In our analysis, twelve histone demethylases showed gene upregulation in prostate cancers, of which six (KDM1A, KDM4B, KDM5B, KDM5C, KDM7A, and PHF8) were in line with previous reports." (PMID 36776320, 2023). "KDM5B depletion also reduces P110α and PIP3 levels and subsequently inhibits the proliferation of human prostate cancer cells." (PMID 35805040, 2022). "Lysine-specific demethylase 5B (KDM5B/PLU1/JARID1B) is found to be overexpressed in numerous malignancies, including breast, lung, skin, liver, and prostate cancer." (PMID 32751840, 2020). "Furthermore, research has demonstrated that KDM5B regulates the androgen receptor and interacts with the PI3K/AKT pathway, contributing to the progression of prostate cancer." (PMID 39239542, 2024). "KDM5B (also called PLU-1) is raised in breast and prostate cancers." (PMID 37107631, 2023). "Of note, search of COSMIC and TCGA databases indicates that KDM5B and HEXIM1 mutations are not common occurrences in breast and prostate cancer." (PMID 31805991, 2019). "The combined inhibition of KDM5B and LSD1 with the use of CPI-455 and namoline, respectively, led to reduced expression of AR-responsive genes and reduced cell proliferation and invasion in both castration-sensitive and castration-resistant prostate cancer cells." (PMID 40940894, 2025).
gastric cancer (25 papers, 2016 to 2025). A primary or metastatic malignant neoplasm involving the stomach. "We showed that KDM5B levels in stomach cancer tissues were much higher than those in adjacent normal mucosa tissues, which was consistent with the analysis of the TCGA database." (PMID 38862740, 2024). "Further assays showed that KDM5B was detected in gastric cancer cell lines HGC27, MKN45, MKN28, and AGS, as well as in Hs738 and primary CAFs and NFs." (PMID 38862740, 2024). "Accordingly, KDM5B knockdown with shRNA significantly suppressed gastric cancer cell proliferation, invasion, and migration in wound-healing, transwell, and clone formation assays." (PMID 38862740, 2024). "Reduction in KDM5B ubiquitination mediated by PIAS4 promotes adaptation of gastric cancer cells to hypoxia." (PMID 38842683, 2024). "KDM5B is a demethylase that has been shown to play a carcinogenic role in a variety of tumors, such as glioma, liver cancer, gastric cancer, colon cancer and laryngeal cancer." (PMID 38789418, 2024). "Lysine[K]-specific demethylase 5B (KDM5B) was identified as an IL-8 transcription factor in CAFs, and the binding of KDM5B to phosphorylated RB1 limited the transcriptional regulation of IL-8 in gastric cancer cells." (PMID 38862740, 2024). "An anoxic microenvironment is a challenge that tumors must adapt to and overcome in order to survive, and in the anoxic environment, gastric cancer cells adapt to anoxic conditions by upregulating lysine-specific demethylase 5B (KDM5B)." (PMID 37777749, 2023). "NEK2 has been demonstrated to inhibit gastric cancer cells proliferation, migration and tumor growth by activating the KDM5B/H3K4me3 signaling pathway." (PMID 37233832, 2023). "For instance, a recent study demonstrated that NEK2 regulated the expression of KDM5B/H3K4me3 through β-catenin/Myc, resulting in the promotion on cell proliferation, migration, and tumor growth of gastric cancer." (PMID 35031599, 2022). "In this study, we found that SUMOylation-dependent stabilization of KDM5B is important to confer hypoxia adaption in gastric cancer." (PMID 34977006, 2021). "In this study, we reported KDM5B was upregulated in gastric cancer; this upregulation of KDM5B enabled the survival of gastric cancer cells by inhibiting the transcription of CDKN1A (p21)." (PMID 34977006, 2021). "Pyrazole derivatives 27 were synthesized and screened for their KDM5B inhibitory activity as potential gastric cancer agents." (PMID 32326131, 2020). "The pyrazole derivatives are promising candidates for targeting KDM5B inhibition and as a new therapeutic strategy for gastric cancer treatment." (PMID 32326131, 2020). "The capability of compound 27a to stabilize KDM5B in a dose-dependent manner and induce the accumulation of H3K4me2/3 in the gastric cancer cell line MKN45, supports the use of compound 27a as a potent and cellular active KDM5B inhibitor." (PMID 32326131, 2020). "KDM5B downregulation retards the outgrowth of gastric cancer." (PMID 38842683, 2024). "Similar to KDM5A, KDM5B is found to be highly expressed in cisplatin‐resistant gastric cancer cells, which could recruit X‐ray Repair Cross Complementing 1 (XRCC1) through demethylation of H3K4, resulting in cisplatin resistance." (PMID 37638338, 2023). "In addition to gastric cancer, KDM5B is also highly expressed in other drug‐resistant tumor cells (such as endometrial cancer cells, melanoma, and NSCLC) and it promotes drug resistance." (PMID 37638338, 2023). "Previous research showed that KDM5B blocked the proliferation of gastric cancer cells." (PMID 37185734, 2023). "Also, another work uncovered that KDM5B silencing contributed to repression of gastric cancer cell proliferation, migration and invasion in vitro." (PMID 33829656, 2021).
gastric cancer (continued). "A previous study suggested that KDM5B, a histone demethylase, demethylated H3K4me3 to an inactive transcription state and reduced the transcription of tumor suppressor genes, then promoted gastric cancer cell proliferation and migration." (PMID 33799631, 2021). "Herein, we found that lysine-specific demethylase 5B (KDM5B) was upregulated in gastric cancer (GC) under hypoxia conditions." (PMID 34977006, 2021). "Increased levels of KDM5A, KDM5B and FBXL10 have also been observed in hepatocellular carcinoma, gastric cancer, lung cancer, pancreatic ductal adenocarcinoma, bladder cancer, colorectal cancer and prostate cancer." (PMID 31160694, 2019). "By targeting KDM5B and HSP90, JIB-04 overcomes chemoresistance in gastric cancer." (PMID 40664642, 2025). "ChIP-qPCR and agarose gel electrophoresis assays indicated that KDM5B could directly bind to the promoter region of IL-8 in CAFs, but not in the gastric cancer cell line AGS." (PMID 38862740, 2024).
lung carcinoma (20 papers, 2010 to 2025). "Transfection of KDM5B-specific siRNA into various bladder and lung cancer cell lines significantly suppressed the proliferation of cancer cells and increased the number of cells in sub-G1 phase." (PMID 20226085, 2010). "In this study, we demonstrated the significant up-regulation of KDM5B in bladder and lung cancers as well as various other cancer types, using quantitative RT-PCR, immunohistochemistry, and microarray-based gene expression profiles." (PMID 20226085, 2010). "The comparative box plots between the normal tissue (left plot) and lung cancer tissues (right plot) indicate that a significantly higher expression level of KDM5B and KDM5C is detected in the NSCLC patients, with KDM5B being more prominent." (PMID 30092824, 2018). "Moreover, there is increasing evidence that KDM5B silences the AMPK pathway whereas miR‐448 activates it,18, 29 and that activation of the AMPK pathway inhibits the malignant phenotypes of lung cancer." (PMID 33829656, 2021). "KDM5B expression rate was found to be highly elevated in neoplastic tissues, in contrast to normal tissues, irrespective of lung carcinoma histology." (PMID 32751840, 2020). "Knockdown of LSD-1 (KDM1) and JARID1B (KDM5B) that mediate demethylation of mono-, di-, and trimethylated H3K4, or the histone lysine methytransferase KMT6 that mediateds trimethylation of H3K27 significantly enhanced DAC-mediated activation of MAGE-A genes in lung cancer cells." (PMID 30185218, 2018).
hepatocellular carcinoma (19 papers, 2016 to 2025). A malignant tumor that arises from hepatocytes. "KDM5B is overexpressed in hepatocellular carcinomas, especially those associated with hepatitis B virus." (PMID 38004468, 2023). "Further research has revealed that the knockdown of KDM5B significantly inhibits the proliferation of hepatocellular carcinoma cells both in vivo and in vitro by arresting the cell cycle at the G1/S phase, partly by up-regulating P15 and P27." (PMID 37185734, 2023). "Histone methylation plays important roles in mediating the onset and progression of various cancers, and lysine‐specific demethylase 5B (KDM5B), as a histone demethylase, is reported to be an oncogene in hepatocellular carcinoma (HCC)." (PMID 33829656, 2021). "KDM5B contributes to hepatocellular carcinoma progression through the miR-448/YTHDF3/ITGA6 axis, and KDM5B inactivates PTEN, while silencing KDM5B reduces tumor cell proliferation and induces cell cycle arrest." (PMID 38004468, 2023). "ETV (KDM5B inhibitor) significantly improves the hepatic histopathology and reduces CHB progression, decreasing the likelihood of hepatocellular carcinoma development and increasing the survival rate of patients with hepatitis-virus-related liver tumors." (PMID 38004468, 2023). "KDM5B was often upregulated in hepatocellular carcinoma (HCC) samples, compared to corresponding non-neoplastic tissues." (PMID 32751840, 2020). "KDM5B was frequently up-regulated in hepatocellular carcinoma (HCC) specimens compared with its expression in adjacent non-tumor tissues." (PMID 27974677, 2017). "Related studies have shown that KDM5B inhibits the expression of PTEN at the transcriptional level through H3K4 demethylation, thus inhibiting phosphorylated PI3K and AKT and increasing the proliferation, migration and invasion of hepatocellular carcinoma cells in vivo and in vitro." (PMID 35493099, 2022).
non-small cell lung carcinoma (13 papers, 2010 to 2025). A group of at least three distinct histological types of lung cancer, including non-small cell squamous cell carcinoma, adenocarcinoma, and large cell carcinoma. "In addition, overexpression of KDM5B was related to the histologic type, clinical stages, lymph node metastasis, and poor prognoses of patients with human laryngeal squamous cell carcinoma and non-small cell lung cancer, indicating its potential diagnostic role." (PMID 35333349, 2022). "Conversely, KDM5B overexpression led to a radioresistant phenotype in non-small cell lung cancer and PCa cell lines." (PMID 34103085, 2021). "Herein, clinical samples of non-small cell lung cancer showed lower RT response rates when higher levels of KDM5B were detected." (PMID 34103085, 2021). "Moreover, in non-small-cell lung cancer, KDM5B activates the c-MET pathway, leading to worse prognoses and triggering resistance to radiation treatment." (PMID 38004468, 2023). "Interestingly, KDM5B was found to promote the radio-resistance of non-small cell lung cancer through the decline of PTEN expression." (PMID 35333349, 2022). "The expression of KDM5B promotes the invasiveness of non-small-cell lung cancer (NSCLC)." (PMID 35493099, 2022). "Importantly, elevated KDM5B expression was observed in both non-small cell lung cancers and small cell lung cancers, indicating that KDM5B overexpression is involved widely in lung carcinogenesis." (PMID 20226085, 2010). "PBIT is a potent, selective inhibitor of KDM5B that reduces the expression of JARID1B, which results in decreased levels of cancer stem cell (CSC) and epithelial-mesenchymal transition (EMT) markers in cisplatin-resistant non-small cell lung cancer." (PMID 39620228, 2024). "This study was conducted with the main objective of investigating the potential role of miR-320a in radioresistance of non-small cell lung cancer (NSCLC) via the possible mechanism related to HIF1α, KDM5B, and PTEN." (PMID 33304897, 2020). "The expression profiles of KDM5B, also known as JARID1B/PLU-1, were up-regulated significantly in various types of cancer compared with corresponding normal tissue, especially in bladder cancer and non-small cell lung cancer (NSCLC)." (PMID 30344945, 2018).
breast tumor (11 papers, 2016 to 2025). "Furthermore, ER+ breast tumors with high KDM5B activity were associated with worse clinical outcome and resistance to endocrine therapy, suggesting that therapeutic targeting of KDM5B might be a potential anticancer strategy." (PMID 27974677, 2017). "mRNA expression profiles from TCGA datasets revealed significantly higher KDM5B expression levels in breast tumors compared to normal tissues." (PMID 40764352, 2025). "In line with global data, KDM5B expression was significantly elevated in breast tumors compared to normal breast tissues (P < 0.0001)." (PMID 40764352, 2025). "Further analysis using UALCAN database confirmed that KDM5B gene expression was significantly higher in breast tumors than in normal breast tissues." (PMID 40764352, 2025). "Lysine demethylase 5B (also known as KDM5B) is upregulated in breast tumors and play an important role in lipid metabolic reprogramming." (PMID 33489906, 2020). "A recent study clearly demonstrated the knockdown of KDM5B reversed the EMT process to inhibit breast tumor cell migration by activating AMPK signaling-mediated lipid metabolism." (PMID 33489906, 2020). "We recently found two microRNAs which specifically target and repress KDM5B which are strongly down-regulated in breast tumors." (PMID 31060229, 2019). "KDM5B, a H3K4me2/3 histone demethylase, has been reported to be overexpressed in human breast tumors and proposed to have an oncogenic role." (PMID 31776402, 2019). "In addition, RNA-Seq data from the TNMplot database demonstrated increased KDM5B expression in both primary breast tumors and metastatic breast cancer samples compared to normal breast tissue." (PMID 40764352, 2025). "In addition, in syngeneic mouse breast tumor models and xenotransplantation models, KDM5B knockout leads to upregulation of tumor suppressor genes such as BRCA1, CAV1, and HOXA5 and increased H3K4 methylation in the chromatin regions of these target genes." (PMID 35493099, 2022). "The current study highlights the over-expression of KDM5B in human breast tumors compared to non-neoplastic breast tissues in global databases as well as in our patient cohort." (PMID 40764352, 2025). "Known inhibitors of KDM5B were also able to induce HEXIM1 expression, inhibit cell proliferation, induce differentiation, potentiate sensitivity to cancer chemotherapy, and inhibit breast tumor metastasis." (PMID 31805991, 2019).